MTOR (mechanistic target of rapamycin kinase)
Diseases named in the same sentence as MTOR in open-access papers (continued):
Sharing a sentence is not in itself a finding about the gene and the disease.
meningioma (continued). "Our aim was to target Pi3kinase upstream mTor, and MAP kinase pathway, overactivated in meningiomas, alone or in combined targeting in comparison to mTor targeting." (PMID 36139608, 2022). "The argument for using mTOR inhibitors in the management of meningioma must be counterbalanced with the potential adverse effects." (PMID 35216092, 2022). "A recent phase II CEVOREM trial showed that the combination of everolimus, an mTOR inhibitor, and octreotide, a somatostatin agonist, has an antiproliferative effect on meningiomas (NCT00972335)." (PMID 35712491, 2022). "Among the ongoing clinical trials in patients with meningiomas, two are assessing the efficacy of mTOR or FAK inhibitors in recurring or progressing cases (NCT02523014, NCT03071874)." (PMID 35049691, 2022). "Our group has demonstrated that the mTOR inhibitor everolimus is efficient both in vitro and clinically to control cell proliferation and tumor growth of meningiomas." (PMID 36139608, 2022). "In IOMM-Lee and HKBMM malignant meningioma cells, gemcitabine enhanced the growth inhibitory effects of the mTOR inhibitor everolimus, the clinical benefits of which have been demonstrated in patients with meningioma." (PMID 35406478, 2022). "Recent clinical trials have investigated novel chemotherapeutic agents for mTOR inhibition, showing promising results in resistant or recurrent meningiomas." (PMID 35216092, 2022). "Among the different mTOR inhibitors available, everolimus has been the most widely used in oncology and was utilized in the published in vivo work on meningioma thus far." (PMID 35216092, 2022). "A phase II clinical trial has demonstrated a positive response in a group of 20 recurrent meningiomas after administration of octreotide combined with the mTOR inhibitor everolimus." (PMID 33899156, 2022). "In conclusion, new clinical trials with larger cohorts are necessary to fully reveal the role of mTOR inhibitors in meningioma." (PMID 35216092, 2022). "Our findings indicated that chrysophanol inhibits OGN/mTOR signaling but induces NF2 signaling in meningioma cells." (PMID 33622177, 2021). "Activation of the PI3K/Akt/mTOR signaling pathway has been correlated with aggressiveness of human meningioma." (PMID 34408780, 2021). "ATK1 and PIK3CA are associated with the MTOR signaling pathway and act with TRAF7 in approximately 10–15% of all meningiomas and, interestingly, over 30% of all cancers." (PMID 34638590, 2021). "mTOR signaling has also been identified as a target of Merlin inhibition, and therefore mTOR inhibitors are being studied shown to be effective at inhibiting growth of meningioma cells in animal models." (PMID 34638590, 2021). "HBL-52 meningioma cells overexpressing OGN showed increased levels of activated mTOR and down-regulated NF2 protein at 48 h (p< 0.05)." (PMID 33622177, 2021). "We found that curcumin blocks hepatocyte growth factor- (HGF-) induced proliferation, migration, invasion, and EMT of human malignant meningioma cells by regulating the PI3K/Akt/mTOR signaling pathway." (PMID 34408780, 2021). "High expression of mTOR is closely related to the tumor deterioration and poor survival time in meningioma." (PMID 33622177, 2021). "The PI3K/Akt/mTOR signaling pathway has been shown to be activated in aggressive meningioma, while mTOR inhibitors were found to suppress meningioma tumor cell proliferation." (PMID 34408780, 2021). "Another study demonstrated that the high expression of mTOR in atypical meningioma led to an increase in mitotic index, and meningioma which had high expression of mTOR exhibited worse prognosis." (PMID 33042832, 2020). "Here we demonstrate that KLF4K409Q mutation in meningioma leads to an upregulated HIF-1α pathway, leaves cells susceptible to hypoxia and that this effect can be blocked by mTOR inhibition with Temsirolimus." (PMID 32245394, 2020).
meningioma (continued). "We have shown previously that the mTOR (mammalian target of rapamycin) inhibitor Temsirolimus is a promising agent in meningioma treatment." (PMID 32245394, 2020). "AKT1 mutations result in downstream activation of the mTOR oncogenic pathway and SMO mutations cause activation of the Hedgehog signaling pathway rendering increased proliferation of meningioma cells." (PMID 32742192, 2020). "The factors involved in the AKT/mTOR pathway have been known to participate in the tumorigenesis and tumor progression of pituitary adenoma and meningioma." (PMID 31665029, 2019). "Some studies reported that the PI3K/AKT/mTOR pathway plays an important role in pituitary adenoma and meningioma." (PMID 31665029, 2019). "mTOR pathway inhibitors are under clinical trial in recurrent and progressive meningiomas with AKT1 or PI3K pathway alterations." (PMID 28713588, 2017). "In this study, we compared the effects of pasireotide to those of octreotide in vitro on meningioma primary cell cultures, both alone and in combination with the mTOR inhibitor everolimus." (PMID 28903425, 2017). "Recent work has demonstrated that there exist two broad classes of meningiomas based on their mutational profile: those driven by NF2 inactivation, and those with non-NF2 driver gene alterations, such as mTOR and Hedgehog pathway alterations." (PMID 28552950, 2017). "Several biological pathways in meningioma oncogenesis, including loss of NF2 and mutation of AKT1, are postulated to exhibit their oncogenic effects through activation of the mTOR mitogenic pathway, leading to uncontrolled neoplastic growth." (PMID 28923059, 2017). "Recent advances in understanding the physiopathology of meningiomas have identified new therapeutic targets in the Pi3K-Akt-mTOR pathway." (PMID 28903425, 2017). "Meningioma samples have been shown to express high levels of mTORC1, indicating mTOR signalling as a relevant pathway in meningioma development." (PMID 28708856, 2017). "The mTOR inhibitor everolimus has been shown to inhibit meningioma cell proliferation in vitro and meningioma xenograft growth in nude mice." (PMID 28903425, 2017). "We recently demonstrated an in vitro additive effect of octreotide and the mTOR inhibitor everolimus on meningiomas, leading to an ongoing clinical trial (NCT02333565)." (PMID 28903425, 2017). "In conclusion, α-synuclein upregulation contributes to aggressive phenotypes of meningiomas via the Akt/mTOR pathway and thus represents a potential therapeutic target for malignant meningiomas." (PMID 27895530, 2016). "Pharmacological inhibition of mTOR signaling was reported to impair meningioma growth in mouse models." (PMID 27895530, 2016). "In conclusion, α-synuclein is upregulated in atypical and anaplastic meningiomas compared to benign tumors and α-synuclein upregulation contributes to the aggressive behavior of meningioma cells via the Akt/mTOR pathway." (PMID 27895530, 2016). "Inhibition of the mTOR pathway in meningiomas may result in AKT compensatory activation, reducing therapeutic efficacy." (PMID 40787520, 2025). "PI3K/Akt/mTOR pathway targeting was justified by its putative role in the tumorigenesis of meningiomas that may stem from NF2 inactivation." (PMID 40149634, 2025). "Furthermore, a Phase II clinical trial (NCT03071874) has shown that Vistusertib, a dual mTOR inhibitor, can slow the growth rate of meningiomas in patients with recurrent WHO grade 2 and 3 meningiomas." (PMID 40113789, 2025). "Another pathway with a dominant role in meningioma development is that of Pi3K/Akt/mTOR." (PMID 38919490, 2024). "This function ties into the role of mTOR with the redox homeostasis of meningioma cells." (PMID 35216092, 2022). "Moreover, this review has shown the great potential of mTOR inhibitors in the treatment of refractory meningioma." (PMID 35216092, 2022). "Targeting the mTOR pathway in meningioma via alternative therapies has yet to be explored." (PMID 35216092, 2022).
meningioma (continued). "Given mTOR’s function in the control of DNA methylation, combining such drugs with mTOR inhibitors may have the potential to produce a synergistic response in meningioma." (PMID 35216092, 2022). "Thus, targeting mTOR activity in meningioma has the potential to disrupt many crucial parts of tumor viability." (PMID 35216092, 2022). "Overall, this review presents the current understanding of mTOR activity in meningioma cells." (PMID 35216092, 2022). "The current understanding of the mTOR pathway heavily involves it in the development of meningioma." (PMID 35216092, 2022). "As a consequence, in vitro data suggest that mTOR inhibitors may be beneficial in treating meningioma." (PMID 35216092, 2022). "The review provided much evidence linking the mTOR pathway to the pathogenesis of meningioma." (PMID 35216092, 2022). "Very few in vivo studies have been conducted on mTOR inhibitors in meningioma treatment." (PMID 35216092, 2022). "Among these targets, mTOR is of particular interest because the efficacy of everolimus, an inhibitor of mTOR, for progressive meningioma was demonstrated in combination with octreotide, a somatostatin analog, in a phase II clinical trial with encouraging findings." (PMID 35406478, 2022). "The upregulation of α-synuclein is thought to contribute to aggressive phenotypes of meningiomas via the Akt/mTOR pathway, thus highlighting a possible role for Hsp110 in the development of malignant meningiomas by regulating the conformational stability of α-synuclein." (PMID 33525518, 2021). "The PI3K/Akt/mTOR pathway is one of the major signaling pathways downstream of c-MET activation and is associated with cell metastasis, invasion, and EMT of cancer cells, including meningioma cells." (PMID 34408780, 2021). "To further investigate the effects of the PI3K/Akt/mTOR pathway on HGF-induced meningioma cells, we treated IOMM-Lee cells with a c-MET inhibitor (SU11274, 5 μmol/l) and a PI3K inhibitor (LY29400225, μmol/l), respectively, and then the proliferation, migration, invasion, and EMT were detected." (PMID 34408780, 2021). "A study of human meningioma cell lines found that meningioma with over-expression of osteoglycin (OGN) exhibited higher cell proliferation, cell cycle activation and colony formation rate, activities closely associated with the PI3K/Akt/mTOR pathway." (PMID 33042832, 2020). "For instance, mTOR inhibitors vistusertib and everolimus (the latter in combination with a somatostatin analog, octreotide) are currently tested in clinical trials for recurrent meningiomas (NCT03071874 and NCT02333565, respectively)." (PMID 32724039, 2020). "The Akt/mTOR pathway has been suggested to be involved in the pathogenesis of meningiomas." (PMID 27895530, 2016). "Activation of the Akt/mTOR pathway is involved in the development and progression of meningioma." (PMID 27895530, 2016). "Thus, mTOR inhibitors may have the potential to benefit patients with incomplete resection of skull-based meningiomas." (PMID 35216092, 2022). "TRAF-7 mutated meningiomas demonstrated elevated levels of programmed death ligand-1 (PD-L1), the major ligand for the programmed death checkpoint pathway, while PD-L2 is highly expressed in PI3K/AKT/mTOR pathway mutations and CTLA-4 was frequently expressed in PIK3CA and SMO mutated tumors." (PMID 36033542, 2022). "Another particular characteristic of atypical meningiomas found in the present work, was phosphorylation of FRAP_2443_2455, DESP_2842_2854, CDC2_154_169, and CA2D1_494_506 peptides, suggesting activation of the MTOR signaling as well as dysregulation in cascades controlling calcium, and cell cycle." (PMID 29391485, 2018). "Thus STAT3 activation may be via several cytokine/growth factor receptor/kinases and/or by the MEK-1-MAPK and PI3k-Akt-mTOR pathways that we and others have found to be mitogenic to meningioma cells." (PMID 24188277, 2013).
meningioma (continued). "Currently, the most widely used pharmacological compounds in the treatment of high-grade and recurrent meningiomas or in cases in which surgical and/or radiotherapy treatment are found to be ineffective are anti-VEGF molecules and mTOR inhibitors." (PMID 37760490, 2023). "Strong expression of SSTR2A receptors, inhibition of the osteoglycin/mTOR pathway, and activation of NF2 signaling promote apoptosis in malignant meningioma cells." (PMID 35712491, 2022). "As described later, these insights into the molecular biology of meningiomas have identified targets for pharmacological agents such as tyrosine kinase inhibitors that subsequently also decrease activation of the PI3K, mTOR, and ERK pathways." (PMID 35402234, 2022). "In summary, this present observation demonstrates the inhibitory effect of chrysophanol on malignant meningioma cells and its regulatory roles in the signaling transduction of OGN/mTOR and NF2 cascades." (PMID 33622177, 2021). "For example, it has been reported that chrysophanol inhibits the osteoglycin/mTOR and activates NF2 signaling pathways to reduce viability and proliferation of malignant meningioma cells." (PMID 34519612, 2021). "For example, OGN promotes meningioma cell proliferation by interacting with other drivers of tumor development, including neurofibromatosis 2 (NF2) and mammalian target of rapamycin (mTOR)." (PMID 33622177, 2021). "Especially in patients with higher-grade meningiomas, the promising data regarding drug therapy with VEGF inhibitors, mTOR inhibitors or tyrosine kinase inhibitors should be considered." (PMID 33922009, 2021). "These agents target meningioma pathological relevant molecules and signaling pathways, including RTKs, Raf, PI3K, mTOR, MEK, WNT/β-catenin, and Hedgehog/Smoothened." (PMID 32642722, 2020). "Compared with SPAs and SMs, the protein p-AKT (phosphorylated at Ser473), p-mTOR (phosphorylated at Ser2448) all showed increasing expression trend, and MEN1 showed reducing expression trend in pituitary adenoma and meningioma samples of PAM." (PMID 31665029, 2019). "We found that the PI3K/mTOR/AKT and SMO pathways were activated in 75% of human meningioma cell lines." (PMID 28552950, 2017). "To explore the possible therapeutic avenues in the setting of OGN overexpression in meningioma and its activation of mTOR and AKT, we tested the effect of a small molecule inhibitor of AKT (AKTVIII) on meningioma cells." (PMID 28923059, 2017). "Also, even though mTOR signalling is an important pathogenic factor for established meningiomas, its blockage might not inhibit initial meningioma development." (PMID 28708856, 2017). "The effects of cucurbitacin I on cerebrospinal fluid stimulation of meningioma cell DNA synthesis phosphorylation/activation of JAK1, STAT3, pMEK1/2, p44/42MAPK, Akt, mTOR, Rb and caspase 3 activation were analyzed in human leptomeningeal and meningioma cells." (PMID 24188277, 2013). "In summary, mTOR pathway activation via AKT1 or PIK3CA mutations promotes cell proliferation and acts together with TRAF7 dysfunction in meningiomas without KLF4 co-mutations." (PMID 41372821, 2025). "PIK3CA co-mutations are also found in meningiomas with TRAF7 mutations but without KLF4 mutations, and PIK3CA is also associated with activation of mTOR signaling, as with AKT1 alterations." (PMID 41372821, 2025). "Additionally, a Phase 2 trial has demonstrated that the combination of octreotide and the mTOR inhibitor everolimus exhibits clinical activity and reduces tumor growth in WHO grade 1–3 meningiomas." (PMID 40787520, 2025).
meningioma (continued). "Loss of function of the Merlin protein – a negative regular of mTOR encoded by the NF2 gene – leads to overactivation of this pathway and subsequent meningioma oncogenesis." (PMID 38919490, 2024). "Furthermore, KLF4-K409Q-expressing meningioma cells show high levels of PI3K-AKT-mTOR pathway activation and respond to mTOR inhibitors." (PMID 38571886, 2024). "Other checkpoint proteins expressed include PD-L2 and B7-H3 in meningiomas with alterations in the PI3K/AKT/mTOR pathway genes, CTLA-4 in CD3+ T cells in atypical meningiomas with PIK3CA or smoothened, frizzled class receptor (SMO) mutations, and the cancer/testis antigen NY-ESO-1." (PMID 37366884, 2023). "Patients 21 and 23 with meningioma CNS WHO grade 3 were also treated with everolimus followed by everolimus plus bevacizumab (patient 21), or everolimus alone (patient 23) due to mTOR pathway activation in Phospho-IHC for three/one and four months, respectively until tumor progression." (PMID 35864412, 2022). "Furthermore, NF2 is a commonly defective gene in meningioma and is understood to be a negative regulator of mTOR, therefore NF2 deletion will drive meningioma proliferation." (PMID 35216092, 2022). "Nevertheless, previous studies have been conducted on the potential of mTOR as a prognostic factor with limited results, though this study provided no comparison with different meningioma histotypes and did not provide any quantitative data on mTOR expression." (PMID 35216092, 2022). "More recently, human clinical trials utilizing mTOR inhibitors have begun enrolling patients including a phase II study examining everolimus and octreotide in patients with recurrent mostly grade II or III meningiomas." (PMID 34638590, 2021). "However, a second mTOR inhibitor, AZD2014 or vistusertib, is also under evaluation for use in meningioma (NCT03071874 and NCT02831257)." (PMID 31970090, 2019). "While PI3K inhibition alone may not induce apoptosis – similar to mTOR inhibition – preclinical data from primary meningioma cell lines suggest that MEK inhibition can trigger caspase-mediated cell death." (PMID 40787520, 2025). "Thus, investigating the expression and activation of OGN, mTOR, and NF2 signaling in meningioma cells will not only uncover key molecular mechanisms, but may also provide promising targets for the treatment of meningioma." (PMID 33622177, 2021). "The fact that metformin inhibits mTOR in experimental models but shows no inhibitory effects on meningioma development, where mTOR signalling plays an important role, may be explained by several factors." (PMID 28708856, 2017). "Antidiabetic doses of metformin may not be sufficient to inhibit mTOR in meningioma development, though metformin passes the blood-brain barrier." (PMID 28708856, 2017). "Notably, our data showed that α-synuclein silencing significantly decreased the phosphorylation of Akt, mTOR, p70S6K, and 4EBP in IOMM-Lee cells, which provides a mechanistic explanation for the regulation of aggressive phenotypes of meningioma cells by α-synuclein." (PMID 27895530, 2016). "To date, there are no molecular targets for meningiomas that have achieved a level of ESCAT I. At best, mTOR pathway activation and NF2 alterations have attained an ESCAT II designation." (PMID 40149634, 2025). "OGN is known to interact with p-mTOR and NF2 during meningioma development, but how OGN affects these other proteins is not clear." (PMID 33622177, 2021).